ZEB1 (zinc finger E-box binding homeobox 1)
Diseases named in the same sentence as ZEB1 in open-access papers (continued):
Sharing a sentence is not in itself a finding about the gene and the disease.
kidney damage (1 paper, 2023). "After this procedure, the rats were accompanied for 12 and 24 weeks after T1D induction and the renal function, structure, cell transdifferentiating markers and zinc finger e-box binding homeobox 1/2 (ZEB1/ZEB2) contribution to kidney damage were evaluated during the DKD progression." (PMID 37391399, 2023).
large cell lung carcinoma (1 paper, 2024). "Based on 2015 WHO classification criteria in redefining large cell lung carcinoma, the expression of specific markers (TTF1, Napsin A, P 40, CK5/6, CK, vimentin and ZEB1) is analyzed by immunohistochemistry." (PMID 39064008, 2024).
lentivirus infection (1 paper, 2023). Virus diseases caused by the Lentivirus genus. "To examine whether USP22 affected the histone H2Bub or ZEB1 recruitment to the VEGFA-promoter I region, we first constructed HCCLM3 cell lines with stable knockdown of USP22 (shUSP22) by lentivirus infection, a scramble shRNA as a control (shCtrl)." (PMID 36906615, 2023).
Listeria infection (1 paper, 2023). "We have shown that DC-specific Zeb1-deficient mice had a selective reduction in splenic cDC1 accompanied by excessive cell death, which rendered them more resistant to Listeria infection." (PMID 37863917, 2023). "Here we observe a selective reduction of splenic cDC1 accompanied by excessive cell death in mice with Zeb1 deficiency in dendritic cells, rendering the mice more resistant to Listeria infection." (PMID 37863917, 2023). "Collectively, these data suggested loss of Zeb1 in DC enhanced host defense against Listeria infection." (PMID 37863917, 2023). "To investigate the innate immune responses of Zeb1-dcKO mice to Listeria infection, we measured the secretion of inflammatory cytokines into serum of mice within 24 h post infection using enzyme-linked immunosorbent assay (ELISA)." (PMID 37863917, 2023). "To examine the host defense of Zeb1-dcKO mice against listeria infection, we infected WT and Zeb1-dcKO mice intravenously with L. monocytogenes." (PMID 37863917, 2023). "Taken together, these results strongly suggested that the increased resistance to Listeria infection of Zeb1-dcKO mice was likely due to the impaired transmission of Listeria into PALS, resulted from selective reduction of splenic cDC1, as the innate immune response was intact in Zeb1-deficient cDC." (PMID 37863917, 2023).
malnutrition (1 paper, 2014). Inadequate nutrition resulting from poor diet, malabsorption, or abnormal nutrient distribution. "Therefore cellular stress like hypoxia or malnutrition might activate HIF1α or β-catenin which induce ZEB1 and the global EMT program and finally lead to the induction of ER-stress." (PMID 24498091, 2014).
mastitis (1 paper, 2020). Inflammation of breast tissue during lactation or postpartum due to an obstructed duct or infection. "Additionally, some of the highly connected genes belonging to this module have been found by others to be related to mastitis development, immune response or mammary gland development including FYN, CDH11, CAV1, F11R, ZEB1, ERBB2, and ERBB3." (PMID 32754201, 2020).
medulloblastoma (1 paper, 2016). A malignant, invasive embryonal neoplasm arising from the cerebellum. "Zeb1 expression is elevated in the Sonic Hedgehog (SHH) medulloblastoma subgroup originating from GNPs with persistent SHH activation." (PMID 27178982, 2016).
mesenchymal tumor (1 paper, 2021). "PANC1 cells grown in conditioned media also showed a decrease in the expression of E-cadherin (CDH1) and an increase in expression of zinc finger E-box binding homeobox 1 (ZEB1) and vimentin (VIM), pointing to a PAR1/macrophage-induced mesenchymal tumor state in PDAC." (PMID 34066284, 2021).
mycosis fungoides (1 paper, 2023). Classical mycosis fungoides is the most common type of mycosis fungoides (MF), a form of cutaneous T-cell lymphoma, and is characterized by slow progression from patches to more infiltrated plaques and eventually to tumors. "The purpose of this RNA sequencing study was to investigate the biological mechanism underlying how the transcription factors (TFs) Twist1 and Zeb1 influence the prognosis of mycosis fungoides (MF)." (PMID 36900319, 2023).
myeloid malignancies (1 paper, 2021). "Hematopoietic Zeb1 overexpressing mice do not spontaneously develop T-cell or myeloid malignancies up to 1.5 years of age and appear to have a normal life expectancy." (PMID 34550965, 2021).
myeloma (1 paper, 2024). "Collectively, our gain-of-function and loss-of-function experiments strongly suggest that targeting USP39 modulates the migratory capacity of myeloma cells through the regulation of ZEB1 expression." (PMID 39736693, 2024). "Therefore, we sought to determine whether ZEB1 depletion could mimic the effect of USP39 inhibition on myeloma cell fate." (PMID 39736693, 2024).
myopia (1 paper, 2023). "One proband with the c.1481_1482insTTTT, p.(Lys494Asnfs*12) variant in ZEB1 had both cystic changes of the posterior corneal lamina and high myopia." (PMID 36902444, 2023).
neuronal migration disorders (1 paper, 2022). "Interestingly, prolonged Zeb1 expression in the cerebral cortex leads to subcortical band heterotopia, suggesting that the Zeb1 polarity gene regulatory pathways are involved in neuronal migration disorders distinct from those induced by defective cytoskeletal genes." (PMID 35600073, 2022).
non-small cell lung adenocarcinoma (1 paper, 2020). Type of epithelial lung cancer arising from glandular origin. "Although there is no direct interaction between UBQLNs and ZEB1, loss of UBQLN1 and UBQLN2 in human A549 and H358 non-small cell lung adenocarcinoma cell lines dramatically increases ZEB1 expression to repress E-cadherin and initiate cell migration and invasion." (PMID 32549375, 2020).
osteoarthritis (1 paper, 2023). A noninflammatory degenerative joint disease occurring chiefly in older persons, characterized by degeneration of the articular cartilage, hypertrophy of bone at the margins and changes in the synovial membrane. "ZEB1 was also expressed in CD68+ macrophages in the synovial membrane of PsA patients but it was nearly absent in the synovium of osteoarthritis patients." (PMID 37978290, 2023).
osteonecrosis of (1 paper, 2024). "However, the roles of ZEB1 and type‐H vessels in steroid‐induced osteonecrosis of the femoral head (SONFH) are unclear." (PMID 39686556, 2024).
ovarian endometriosis (1 paper, 2025). A non-neoplastic disorder characterized by the growth of endometrial tissue in the ovaries. "The miR-200b-ZEB1 feedback loop is increased in DIE eutopic endometrium but downregulated in ovarian endometriosis." (PMID 40002936, 2025). "In contrast, in women with uncomplicated ovarian endometriosis, implanting endometrial cells in the ovary increases both ZEB1 and miR-200b expression while decreasing E-CADHERIN expression." (PMID 40002936, 2025).
ovarian epithelial tumor (1 paper, 2017). A benign, borderline, or malignant tumor that originates from the surface epithelium of the ovary. "Ovarian epithelial tumor cells showed concurrent up-regulation of miR-200, down-regulation of the four target genes (ZEB1, ZEB2, TGFβ1 and TGFβ2), and up-regulation of effector genes that were negatively regulated by the target genes." (PMID 28623900, 2017).
ovarian serous cystadenocarcinoma (1 paper, 2022). A malignant serous cystic epithelial neoplasm arising from the ovary. "The positive correlation between HK2 and CDH2, fibronectin, MMP9, ZEB1, ZEB2 and vimentin in OV (ovarian serous cystadenocarcinoma) was confirmed by using TIMER 2.0." (PMID 35953860, 2022).
primary biliary cirrhosis (1 paper, 2023). "H19 was markedly upregulated in primary sclerosing cholangitis and primary biliary cirrhosis, which prevented zinc finger E‐box binding homeobox 1 (ZEB1) inhibition of epithelial cell adhesion molecule (EpCAM), causing EpCAM activation and contributing to biliary hyperplasia." (PMID 37398637, 2023).
psoriasis (1 paper, 2023). An autoimmune condition characterized by red, well-delineated plaques with silvery scales that are usually on the extensor surfaces and scalp. "Our results indicate that ZEB1 expression in macrophages is required for the in vivo anti-inflammatory effects of Metformin in response to LPS and in a mouse model of psoriasis." (PMID 37978290, 2023). "ZEB1 expression in macrophages was also required for the anti-inflammatory and ROS-inhibiting effect of Metformin in both an endotoxin-induced model of acute inflammation as well as in a chronic inflammation model such as psoriasis." (PMID 37978290, 2023). "Next, we examined whether the expression of ZEB1 in PBMCs from healthy controls, septic patients at 0 h and 72 h, and PsA patients correlated with the expression of several markers in our sepsis and psoriasis mouse models." (PMID 37978290, 2023).
pulmonary arterial hypertension (1 paper, 2022). Pulmonary arterial hypertension (PAH) is a group of diseases characterized by mean pulmonary artery pressure >20 mmHg and elevated pulmonary arterial resistance leading to right heart failure. "Conversely, in cells pre-treated with the dual ETAR/ETBR antagonist macitentan, a FDA approved drug for the treatment of pulmonary arterial hypertension, ET-1-induced ZEB1 and YAP/TAZ nuclear accumulation was inhibited." (PMID 35477522, 2022).
reovirus infection (1 paper, 2025). "Having established that ZEB1 is a potent negative regulator of cell-surface JAM-A expression on pancreatic fibroblasts and CAFs, we next aimed to confirm whether ZEB1 ablation would result in increased susceptibility to reovirus infection and reovirus-mediated cell death." (PMID 41244268, 2025). "All in all, this shows that ZEB1 ablation in pancreatic fibroblasts, in addition to causing JAM-A upregulation, can increase their susceptibility to reovirus infection and reovirus-mediated apoptotic cell death." (PMID 41244268, 2025). "Importantly, ZEB1 ablation increased the sensitivity of fibroblasts to reovirus infection and subsequent cell death." (PMID 41244268, 2025). "Therefore, we checked whether there are changes in integrin β1 following ZEB1 KO that could influence potential differences in reovirus infection." (PMID 41244268, 2025). "ZEB1 ablation increases JAM-A expression and sensitizes these fibroblasts to reovirus infection." (PMID 41244268, 2025). "Therefore, targeting of ZEB1 could potentially also restore JAM-A expression in these mesenchymal tumor cells, sensitize them to reovirus infection, and perhaps even revert EMT." (PMID 41244268, 2025).
retinal degeneration (1 paper, 2019). Degeneration of the retina. "Evaluation of regions associated with overt retinal degeneration and RPE phenotypic changes showed decreased detection of the mitochondrial marker COX-IV after PGC-1 deletion, whereas the EMT markers—collagen-VI, vimentin, TWIST1, and ZEB1- were increased." (PMID 31101737, 2019).
sarcoidosis (1 paper, 2023). Sarcoidosis is a multisystemic disorder of unknown cause characterized by the formation of immune granulomas in involved organs. "We found that, unlike their control counterparts, both cardiac and BAL sarcoidosis T cells showed enrichment of memory T cell TF genes (RFX7 and ZEB1), survival and proliferation TF genes (HLF and HIST1H2BN) and type 3 response TF genes (ARNTL and ADARB1)." (PMID 37576111, 2023).
schizophrenia (1 paper, 2021). A major psychotic disorder characterized by abnormalities in the perception or expression of reality. "Finally, ZEB1 was implicated in human schizophrenia in a GWAS region-based analysis that analysed signals from independent 100 kb regions." (PMID 34573345, 2021).
seminoma (1 paper, 2022). A radiosensitive malignant germ cell tumor found in the testis (especially undescended), and extragonadal sites (anterior mediastinum and pineal gland). "All together, these data support the pivotal role of nuclear PTTG1 in driving the invasion-prone cell population of human seminoma, and shed a light on the underlying mechanism in which the interplay with ZEB1 is crucial." (PMID 36230799, 2022). "It is of note that analysis of the Atlas database of testicular tumors supported the in vivo role of the PTTG1/ZEB1/E-CAD axis in human seminoma." (PMID 36230799, 2022). "To further detail the molecular mechanism behind PTTG1/ZEB1 cooperation, we carried out immunoprecipitation in both an unrelated cellular model, 293-T, and in a seminoma cell line." (PMID 36230799, 2022). "In functional assays, we further demonstrated that PTTG1/ZEB1 interaction mediates the securin oncogenic properties in seminoma cell lines." (PMID 36230799, 2022). "Taken together, these results strengthen the role of PTTG1 in the EMT process in human seminomas, focusing its function on the cooperation with the transcriptional repressor activity of ZEB1, specifically on the E-CAD gene." (PMID 36230799, 2022). "RNA depletion and overexpression experiments were performed to verify the role of PTTG1/ZEB1 in E-Cadherin repression and seminoma invasiveness." (PMID 36230799, 2022). "This phenomenon is not coupled with an increase in ZEB1 levels in seminoma, supporting the hypothesis that nuclear PTTG1 cooperates with ZEB1-dependent E-CAD repression in human seminoma tumors." (PMID 36230799, 2022). "In addition, using immunoprecipitation, we demonstrated the interaction of PTTG1 and ZEB1 in human seminoma specimens from patients that underwent therapeutic orchidectomy for seminoma." (PMID 36230799, 2022). "Finally, to further confirm the PTTG1/ZEB1 interplay from a clinical point of view, we analyzed the molecular interaction via immunoprecipitation and confocal microscopy of human seminoma specimens obtained from patients who underwent therapeutic orchidectomy." (PMID 36230799, 2022). "To verify that the observed phenomenon relies on PTTG1, we analyzed ZEB1 levels in seminomas, since an augmented expression in this subclass could belittle PTTG1 role." (PMID 36230799, 2022). "Importantly, we demonstrated the physical interaction of PTTG1 and ZEB1 in human seminoma specimens." (PMID 36230799, 2022). "Taken together, these data support the role of PTTG1/ZEB1 interplay in driving E-CAD repression in vivo, and hence in promoting EMT in specific areas of human seminoma tumors." (PMID 36230799, 2022). "Taken together, these results show for the first time a new co-repressional platform in seminoma cells, indicating that PTTG1/ZEB1 cooperation is essential for PTTG1 to exert its E-CAD regulation." (PMID 36230799, 2022). "To determine whether the role of PTTG1 observed in cell lines has a translational impact in human seminomas, we wondered whether the PTTG1/ZEB1/E-CAD axis was confirmed in human testicular tumors." (PMID 36230799, 2022). "ZEB1 levels were significantly lower in seminomas than in nonseminomas, supporting our hypothesis that PTTG1’s cooperation with ZEB1 is crucial in the transcriptional repression of E-CAD in human seminomas." (PMID 36230799, 2022).
Sepsis (1 paper, 2023). Sepsis is defined as life-threatening organ dysfunction caused by a dysregulated host response to infection. "Taken together, these findings support a model where ZEB1 modulates the inflammatory phenotype of human PBMCs in sepsis and psoriatic disease through amino acid efflux-dependent regulation of mitochondrial translation." (PMID 37978290, 2023). "In addition, we show that Metformin’s anti-inflammatory and ROS-inhibiting effects in models of sepsis and psoriatic disease are dependent on the expression of ZEB1 in macrophages." (PMID 37978290, 2023).
serous ovarian tumors (1 paper, 2017). "In addition to these studies, the mRNA expression levels of E-cadherin and the transcriptional repressors Twist, Snail, Slug and ZEB1, were evaluated in serous ovarian tumors of different FIGO stages from the information available at the TCGA data portal." (PMID 28934230, 2017).
skin aging (1 paper, 2023). The gradual irreversible changes in structure of skin that occur as a result of the passage of time.. "The elucidation of the molecular mechanism of the UV-induced decrement in ZEB1 can provide a new idea for finding active small molecules that ameliorate UV-induced skin aging." (PMID 37149635, 2023). "However, few studies have investigated whether TAGLN can regulate UV-induced skin aging and whether a relationship exists between TAGLN and ZEB1." (PMID 37149635, 2023).
somatotrophinomas (1 paper, 2019). "Upregulation of ZEB1 (zinc-finger E-box binding homeobox 1), one of the master regulators of EMT, had higher mRNA expression (vs. normal pituitary P = 0.005) and increased nuclear protein expression (vs. normal pituitary P = 0.006; vs. sporadic somatotrophinomas P = 0.01)." (PMID 30867568, 2019).
T-cell acute lymphoblastic leukemia (1 paper, 2021). Acute lymphoblastic leukemia of T-cell origin. "Zinc Finger E-Box Binding Homeobox 1 (ZEB1), a transcription factor that acts as a tumor suppressor in T-cell acute lymphoblastic leukemia (T-ALL), is repressed due to histone deacetylation and chromatin condensation at its promoter." (PMID 33927716, 2021).
teratoma (1 paper, 2025). A non-seminomatous germ cell tumor characterized by the presence of various tissues which correspond to the different germinal layers (endoderm, mesoderm, and ectoderm). "This miRNA has been shown to facilitate epithelial-to-mesenchymal transition (EMT) and metastasis by targeting ZEB1 and PTEN, affirming its oncogenic role in pluripotent tumors such as teratomas." (PMID 40869426, 2025).
testicular tumors (1 paper, 2022). "E-Cadherin and ZEB1 levels were analyzed in human testicular tumors from the Atlas database." (PMID 36230799, 2022).
Tetralogy of Fallot (1 paper, 2024). A congenital cardiac malformation comprising pulmonary stenosis, overriding aorta, ventricular septum defect, and right ventricular hypertrophy. "For Tetralogy of Fallot, XGBoost identified a specific gene signature ZEB1 (zinc finger E-box binding homeobox 1, 189909), which has also been validated by a recent publication." (PMID 39202774, 2024).
thymic atrophy (1 paper, 2022). "Particularly, they found that loss-of-Zeb1 results in thymic atrophy due to impaired T cell lineage specification." (PMID 36008379, 2022).
undifferentiated carcinoma (1 paper, 2022). A usually aggressive malignant epithelial neoplasm composed of atypical cells which do not display evidence of glandular, squamous, or transitional cell differentiation. "In mouse cancer models, genetic depletion of ZEB1 in the pancreas is shown to reduce undifferentiated carcinomas, invasion, and metastasis." (PMID 35451213, 2022).
uterine carcinosarcoma (1 paper, 2022). A usually aggressive malignant neoplasm arising from the uterine corpus and less often the cervix. "The current study showed that EMT might promote the development of ECS and uterine carcinosarcoma (UCS), and ZEB1 was highly expressed in the sarcomatous components." (PMID 36172159, 2022).